EAF1 (ELL associated factor 1)
Description:
Acts as a transcriptional transactivator of ELL and ELL2 elongation activities.
Tractability: PROTAC: ubiquitination databases record sites on it; its protein half-life has been measured.
Gene: Protein-coding gene on chromosome 3 (15,427,598 to 15,450,635, forward strand). Ensembl gene ENSG00000144597.
Subcellular location: Nucleus speckle; Nucleus, Cajal body
Subcellular location (Human Protein Atlas): Nuclear bodies; Nucleoplasm; Vesicles
Pathways (Reactome):
Gene expression (Transcription): Formation of RNA Pol II elongation complex; RNA Polymerase II Pre-transcription Events; RNA Polymerase II Transcription Elongation
Gene Ontology:
Molecular function: protein binding; transcription elongation factor activity
Biological process: regulation of transcription elongation by RNA polymerase II; transcription elongation by RNA polymerase II
Cellular component: nuclear body; nuclear speck; transcription elongation factor complex; nucleoplasm; Cajal body; super elongation complex
Genetic constraint (gnomAD): Loss-of-function variants: 18 observed, 26.38 expected, observed/expected ratio (o/e) 0.68, 90% interval 0.47 to 1.01. The upper end of that interval is the gene's LOEUF score, 1.01, which puts it in group 4 of 6, group 1 being the genes least tolerant of losing a copy. Missense variants: 256 observed, 337.36 expected, observed/expected ratio (o/e) 0.76, 90% interval 0.68 to 0.84. Synonymous variants: 102 observed, 121.96 expected, observed/expected ratio (o/e) 0.84, 90% interval 0.71 to 0.99.
Homologues: Orthologues: chimpanzee EAF1 (100% identical), macaque EAF1 (100% identical), guinea pig EAF1 (99% identical), mouse Eaf1 (98% identical), rat Eaf1 (98% identical), pig EAF1 (96% identical), rabbit EAF1 (95% identical), dog EAF1 (94% identical), tropical clawed frog eaf1 (77% identical), zebrafish eaf1 (74% identical), Drosophila melanogaster Eaf (41% identical), Caenorhabditis elegans eaf-1 (26% identical). Paralogues in human: EAF2 (56% identical).
Diseases named in the same sentence as EAF1 in open-access papers:
EAF1 is named in the same sentence as 10 diseases in open-access papers, as found by Europe PMC text mining. Sharing a sentence is not in itself a finding about the gene and the disease. The quoted sentences say what the papers report.
leukemia (2 papers, 2021 to 2023). A malignant (clonal) hematologic disorder, involving hematopoietic stem cells and characterized by the presence of primitive or atypical myeloid or lymphoid cells in the bone marrow and the blood. "ELL-associated factors 1 and 2 (EAF1/2), a class of tumor suppressor genes interacting strongly with eleven-nineteen lysine-rich leukemia (ELL), can inhibit a variety of cancers in organisms, including leukemia and prostate cancer." (PMID 37002435, 2023).
cyst (1 paper, 2023). A sac-like closed membranous structure that may be empty or contain fluid or amorphous material. "It seems that the cyst formation suppressed EAF1 expression." (PMID 36631795, 2023). "However, after cyst removal in 12MPS, EAF1 expression level in sera is still high." (PMID 36631795, 2023).
depression (1 paper, 2023). "Therefore, EAF1 may control the occurrence and development of depression by regulating Wnt/β-catenin pathway, but there is no direct evidence that there is a causal relationship between EAF1 and depression." (PMID 37415981, 2023).
heart failure (1 paper, 2022). Inability of the heart to pump blood at an adequate rate to meet tissue metabolic requirements. "N-glycoproteome profiling of MI day 3 plasma revealed α2-macroglobulin and ELL-associated factor 1 as strong predictors of future MI death and progression to heart failure." (PMID 35089808, 2022).
major depressive disorder (1 paper, 2023). An episode of depression lasting two or more weeks without an intervening episode of mania. "The common genetic characteristics of rheumatoid arthritis and major depressive disorder are EAF1, SDCBP and RNF19B." (PMID 37415981, 2023).
tumor (4 papers, 2010 to 2023). "Many previous studies have focused on the role of the EAF genes in tumor suppressor and transcriptional properties, but paid little attention to the linkage of EAF1 and EAF2 dysfunction with erythropoiesis and hypoxia tolerance." (PMID 37002435, 2023). "ELL Associated Factor 1 (EAF1) is one of the EAF family members, which plays an essential role in tumor suppression and embryogenesis." (PMID 35633787, 2022). "EAF1 serves as a tumor suppressor as well, via the regulation of the canonical WNT/β-catenin pathway, which plays a key role in CRC development." (PMID 33238574, 2020). "Little is known regarding the function of EAF1, but evidence clearly supports a tumor suppressive role for EAF2/U19." (PMID 20161747, 2010). "Given the similarity of these proteins and their similar function in the EAF-Wnt4 feedback loop, the possibility exists that EAF1 might also play an important role in tumor suppression." (PMID 20161747, 2010). "A better understanding of the functional difference between EAF1 and EAF2/U19 will help us to better define the precise roles of EAF1 and EAF2/U19 in embryogenesis and tumor suppression." (PMID 20161747, 2010). "Previous studies have shown that zebrafish EAF1 and EAF2 regulate anterior and posterior pattern during zebrafish embryogenesis by suppressing canonical WNT/β-catenin signaling, which might be the mechanism for EAF1 and EAF2 in tumor suppression." (PMID 37002435, 2023). "Our observation that both EAF1 and EAF2/U19 participate with Wnt4a in a negative feedback loop in zebrafish embryogenesis may shed light on the tumor suppressive function of EAF proteins." (PMID 20161747, 2010).
cancer (1 paper, 2010). A tumor composed of atypical neoplastic, often pleomorphic cells that invade other tissues. "Previous studies indicated that EAF (ELL-associated factor) family members, EAF1 and EAF2/U19, play a role in cancer and embryogenesis." (PMID 20161747, 2010).
EAF1 also shares sentences with these, for which no sentence is quoted: anemia (1 paper); prostate carcinoma (1); rheumatoid arthritis (1).